KDR (kinase insert domain receptor)
Diseases named in the same sentence as KDR in open-access papers (continued):
Sharing a sentence is not in itself a finding about the gene and the disease.
glioma (211 papers, 2008 to 2025). A benign or malignant brain and spinal cord tumor that arises from glial cells (astrocytes, oligodendrocytes, ependymal cells). "The findings of our systematic review and meta-analysis indicate an association between KDR/VEGFR2 (rs2071559) gene polymorphism and the risk of developing gliomas." (PMID 39124599, 2024). "An elevated risk of gliomas was observed in all the genetic models, including dominant (CC + CT vs. TT), recessive (CC vs. CT + TT), CC genotype, CT genotype, and C allele of KDR/VEGFR2 (rs2071559) gene polymorphism." (PMID 39124599, 2024). "Our systematic review and meta-analysis indicates that all genetic models of KDR/VEGFR2 (rs2071559) gene polymorphism significantly increase the risk of gliomas." (PMID 39124599, 2024). "The subgroup analysis also revealed a greater relationship between the KDR/VEGFR2 (rs2071559) gene polymorphism and glioma occurrence in studies where the mean age was ≥42.3 years and the male sex prevalence was <57%, as shown by a higher odds ratio." (PMID 39124599, 2024). "The present study showed that genetic variations in the KDR gene are associated with glioma formation in a Han Chinese population." (PMID 37114147, 2023). "In this study, we assessed the contribution of two potentially functional variants of the KDR gene to the risk of glioma in the Han Chinese population." (PMID 37114147, 2023). "Amplifications and mutations of PDGFRA, KIT and KDR were found in 8-15% of RMPAhigh gliomas, followed by EPHB3 (7.7%), FGFR1 (5.9%), FGFR3 (5.9%) and MET (4.1%)." (PMID 27385209, 2016). "Our meta-analysis from a total of five studies (n = 6010) showed that the C allele of KDR/VEGFR (rs2071559) gene polymorphism was associated with a higher risk of developing gliomas than the T allele [OR 1.41 (95% CI 1.27–1.57), p < 0.001, I2 = 0%, random-effects models]." (PMID 39124599, 2024). "Therefore, our study unveils evidence regarding the involvement of the KDR/VEGFR2 rs2071559 gene polymorphism in the development of gliomas, especially among Asian populations." (PMID 39124599, 2024). "Our pooled analysis of six studies (n = 4828) showed that the recessive model of KDR/VEGFR2 (rs2071559) gene polymorphism (CC vs. CT + TT) was associated with a higher risk of developing gliomas [OR 1.52 (95% CI 1.25–1.85), p < 0.001, I2 = 24%, random-effects models]." (PMID 39124599, 2024). "Our pooled analysis of six studies (n = 4828) showed that the dominant model of KDR/VEGFR2 (rs2071559) gene polymorphism (CC + CT vs. TT) was associated with a higher risk of developing gliomas [OR 1.40 (95% CI 1.24–1.57), p < 0.001, I2 = 0%, random-effects models]." (PMID 39124599, 2024). "However, little is known regarding the association between KDR single nucleotide polymorphisms (SNPs) and glioma susceptibility." (PMID 37114147, 2023). "In particular, rs2071559 and rs2239702 were associated with a higher risk of glioma, indicating that the KDR may act as a suppressor of tumor progression." (PMID 37114147, 2023). "Some reports on the relationship between KDR and glioma susceptibility have been published." (PMID 37114147, 2023). "A study that evaluated the association of VEGF and KDR SNPs in patients with severe gliomas showed that VEGFA-2578 C/A and VEGFA-1154G/A increased the risk of severe glioma and that the “CAGT” haplotype of the KDR gene altered the aggressiveness of high-grade glioma and the risk of grade IV tumors." (PMID 36559251, 2022). "We also still encourage future research that explores the role of other SNPs from KDR/VEGFR2 gene polymorphism in the development of gliomas to provide a better understanding about how changes in VEGFR2 function or expression may contribute to the development of gliomas." (PMID 39124599, 2024).
glioma (continued). "In addition to their immunosuppressive capacity, glioma MDSCs have been associated with tumor angiogenesis because they express KDR (kinase insert domain receptor), also known as VEGFR2, which coordinates immune alterations with vascular defects, favoring the progression of the tumors." (PMID 32570988, 2020). "This systematic review and meta-analysis is the first to thoroughly examine the correlation between KDR/VEGFR2 (rs2071559) gene polymorphism and the risk of gliomas." (PMID 39124599, 2024). "Third, our current research solely investigates the impact of a single SNP, specifically KDR/VEGFR2 rs2071559, on the development of gliomas." (PMID 39124599, 2024). "Previous studies have identified MAPK14 (p38) and KDR as potential tumour suppressors in glioma development and potential antigens for vaccine advancement." (PMID 37865727, 2023). "KDR regulates tumor angiogenesis and migration, previous work has demonstrated that KDR expression is strongly related to clinical outcomes and drug sensitivity in glioma and thyroid cancer." (PMID 36441563, 2022). "VEGF and high-affinity VEGF receptor Flk1/KDR (VEGFR2) are key regulators of glioma angiogenesis, thus, inhibition of VEGFR2 expression would inhibit the development of new blood vessels within the tumor microenvironment (TME) and inhibit glioma progression." (PMID 33790740, 2021). "Only four genes differentially expressed in both LGG and GBM patients (ERBB1, RB1, ESR1, and KDR), indicating putative role in the regulatory of circadian rhythm pathway alteration in glioma." (PMID 34224318, 2021). "Increased levels of circulating KDR+ bone-marrow-derived EPCs were reported in a cancer mouse model, which is compatible with our findings in glioma patients." (PMID 31428150, 2019). "Pair-wise comparison of CNAs in the glioma-associated genes ALK, PDGFRA, VEGFR2/KDR, EGFR, MET and FGFR1 was performed employing MLPA techniques." (PMID 30894200, 2019). "An increase in glioma malignancy grade coincided with an increase in the KDR+ fraction, while the CD133+ cell fraction decreased relatively." (PMID 31428150, 2019). "A recent study reported that in glioma stem cells, autophagy-induced phosphorylation of the kinase insert domain receptor of VEGFR-2 contributes to VM formation." (PMID 31772665, 2019). "In contrast, genes encoding angiogenic factors (ANGPT1, ANGPT2) and receptors (NRP1, and KDR) were highly expressed in SA-culture-derived glioma cells of 51B." (PMID 29113349, 2017). "Co-occurrence between amplification of EPHB3 and alterations in PIK3CA (both at chromosome 3q26-3q27), and amplifications in PDGFRA, KIT and KDR (all at 4q12) were also found in a subset of RMPAhigh gliomas, due to their localization in the common amplicons." (PMID 27385209, 2016). "A well-studied cluster on chromosome 4q containing PDGFRA, KIT, and KDR was amplified in glioma and melanomas." (PMID 24874471, 2014). "In PDGFRA amplified gliomas two genetic rearrangements have been described – a gene fusion between kinase insert domain receptor (KDR) and the PDGRFA gene and PDGFRA (Δ8, 9), an intragenic deletion rearrangement." (PMID 24716189, 2014). "VE-cadherin expression was also attenuated by KDR knockdown in glioma stem-like cells." (PMID 40869298, 2025). "These previous studies suggest that overexpression of KDR may influence cell activity in brain tissues and consequently contribute to glioma formation." (PMID 37114147, 2023). "Furthermore, we found that 5 immune inhibitors (KDR, TIGIT, VTCN1, LAG3 and ADORA2A) and 2 immune stimulators (ICOS and TNFRSF25) were significantly associated with HIC2 in gliomas." (PMID 36650953, 2023). "Moreover, there is a significant correlation between KDR expression and vasculogenesis and angiogenesis in gliomas." (PMID 37114147, 2023). "KDR, COL1A2, and SAMD9 were frequently mutated and highly expressed in gliomas with subtype Ims1." (PMID 34815785, 2021).
glioma (continued). "The quantitative real-time PCR method was used to evaluate mRNA expression of SEMA3(A-G), neuropilins (NRP1 and NRP2), plexins (PLXNA2 and PLXND1), cadherins (CDH1 and CDH2), integrins (ITGB1, ITGB3, ITGA5, and ITGAV), VEGFA and KDR genes in 59 II-IV grade glioma tissues." (PMID 33036421, 2020). "The RMPAhigh gliomas were enriched in immature vessel cells and tumor associated macrophages, and both cell types expressed high levels of pro-angiogenic RTKs including MET, VEGFR1, KDR, EPHB4 and NRP1." (PMID 27385209, 2016). "Immunofluorescence staining showed that cells, expressed simultaneously CD34,CD133,KDR and Hoechst 33342, appeared in the tumors, which proved that EPCs derived from donors incorporated into the tumors and contributed to the growth of glioma." (PMID 22720671, 2012). "Like KDR, those PDGFRA co‐amplified genes are suspected driver genes to promote the progression of glioma." (PMID 36043552, 2023). "We found that TPM4 is related to the molecular targets of glioma, such as CD160, IDO1, IL10, KDR, PVRL2, and TGFB1." (PMID 36639743, 2023). "GDF15 promotes tumor angiogenesis through a positive feedback loop comprising EC-secreted GDF15, glioma-derived VEGFA, and KDR on ECs." (PMID 35280749, 2022). "We further strengthened this argument by correlating the expression of the two VEGFR2 subunit genes FLT1 and KDR with the expression of EFNB2 in Glioma." (PMID 35629359, 2022). "Diffuse gliomas with high expression of COL1A2, SAMD9, and KDR had poor prognoses in the CGGA cohort (log-rank test, P < 0.05), which was consistent with the TCGA cohort." (PMID 34815785, 2021). "In these RMPAhigh gliomas, angiogenic related RTKs including MET, VEGFR1, KDR, EPHB4, NRP1 were frequently and concomitantly expressed in CD45+ immune cells and CD105+ endothelial cells." (PMID 27385209, 2016). "Though gliomas with RMPAlow signature contained fewer CD45+ cells and CD105+ cells, CD45+ cells in these gliomas also expressed VEGFR1, KDR, EPHB4 and PLXNB2." (PMID 27385209, 2016). "TAMs are enriched in the RMPAhigh gliomas and they show high surface expression of MET, VEGFR1, KDR, EPHB4 and NRP1." (PMID 27385209, 2016). "Our current study did not assess the other SNPs from the KDR/VEGFR2 gene as well as other genes that may contribute to the development of gliomas." (PMID 39124599, 2024).
gastric cancer (195 papers, 2003 to 2026). A primary or metastatic malignant neoplasm involving the stomach. "The high expression of FLT1 coupled with low expression of KDR in endothelial cells is also observed in gastric cancer (GC) and hepatocellular carcinoma (HCC), where the expression level of PGF inversely correlates with patient overall survival rates." (PMID 39628692, 2024). "SNPs of PIK3CA (p.Glu707Lys) and KDR (p.Gln472His) were more frequent in gastric cancer patients than in healthy Japanese people (p < 2.2 × 10–16 and p = 0.001, respectively; Bonferroni-corrected significance level = 0.003)." (PMID 34873204, 2021). "In contrast, the currently recommended molecular-targeted therapies for gastric cancer are trastuzumab, which targets erb-b2 receptor tyrosine kinase 2 (ERRB2) (also known as HER2), and ramucirumab, which targets kinase insert domain receptor (KDR) (also known as VEGFR2)." (PMID 35409367, 2022). "Here we have demonstrated novel observations that COX-2 might play important roles in angiogenesis of gastric cancer through regulation of VEGF, Flt-1, Flk-1/KDR, angiopoietin-1, tie-2, MMP2 and OPN." (PMID 21266034, 2011).
hepatocellular carcinoma (190 papers, 2011 to 2026). A malignant tumor that arises from hepatocytes. "KDR was shown to be a regulator of vascular endothelial growth factor–induced tumor development and angiogenesis in murine hepatocellular carcinoma cells." (PMID 34888523, 2021). "In this research, we found that PROZ was a gene related to KDR expression that had significantly low expression in cancer tissue by analyzing the differential genes of cancer tissue and adjacent tissue and the intersection of KDR-related genes in hepatocellular carcinoma." (PMID 36140703, 2022). "Results from experiments in cervical, renal, non-small-cell lung, osteosarcoma, and hepatocellular cancer cells show that miR-497-5p regulates cell growth and proliferation and is associated with the MAPK pathway by targeting several involved genes such as RAF1, KDR/VGFR-2, and IGF1-R." (PMID 33374439, 2020). "The findings from these studies suggest that bFGF collaboratively enhances VEGF-mediated hepatocellular carcinoma development and angiogenesis by upregulating VEGF via KDR/Flk-1." (PMID 38672182, 2024). "External validation confirmed positive correlations for FAP and angiogenesis receptors FLT1, KDR, and KIT as well as HIF1A and ETS1 in hepatocellular carcinoma but also in metastatic prostate cancer (Dream Team cohort)." (PMID 36672341, 2023). "A formulation of Chinese herbs was capable of downregulating the expression of KDR and VEGF in a mouse with hepatocellular carcinoma." (PMID 32316129, 2020). "A double suicide gene system with the KDR promoter, pcDNA3-KDRp-CDglyTK, was constructed and transfected into lung cancer cell lines L9981 and NL9980, and human hepatocellular carcinoma cell line HepG2." (PMID 21418659, 2011). "KDR is overexpressed in different types of cancers, such as breast cancer, cervical cancer, non-small cell lung cancer (NSCLC), hepatocellular carcinoma (HCC), and renal carcinoma." (PMID 35215358, 2022). "CD/TK gene expression was only detected in human large cell lung cancer cell lines L9981 and NL9980, which expressed intrinsic KDR, but not in the human hepatocellular carcinoma cell line HepG2, which did not express intrinsic KDR." (PMID 21418659, 2011). "To investigate the interaction between BMP9 and angiogenic factors in HCC, we first explored the gene expression correlation between BMP9 (GDF2) and the angiogenic proteins VEGFR2 (KDR) and HIF-1α (HIF1A) in The Cancer Genome Atlas Liver Hepatocellular Carcinoma (TCGA-LIHC) cohort." (PMID 35163396, 2022).
Hypertension (186 papers, 2005 to 2026). The presence of chronic increased pressure in the systemic arterial system. "The germline variant rs4864950 T>A in the KDR gene increased the risk of composite toxicity (occurrence of any of hypertension, diarrhea and dermatological reactions) in patients treated with the VEGFR TKIs sorafenib and regorafenib." (PMID 38264526, 2023). "Variations in how this pathway’s genes, including KDR, are expressed have been linked to a higher risk of hypertension." (PMID 37571339, 2023). "Blood pressure and the likelihood of developing hypertension have both been linked to higher KDR expression." (PMID 37571339, 2023). "Two out of 4 patients (50%) harboring a high impact variant in KDR had been diagnosed with systemic hypertension." (PMID 33320693, 2020). "Hypertension and neutropenia, two of the major side-effects observed in fostamatinib (R406) RA clinical trials, have been linked to inhibition of KDR and Jak, respectively." (PMID 26756335, 2016). "The present study showed a significant association of KDR rs1870377 allele and genotype frequency with CR using all inheritance models without adjustment and after adjustment with body mass index, smoking, diabetes, hypertension, age, and sex." (PMID 33665428, 2021). "A previous study has shown CD34 + and CD34 + KDR + cell numbers to be reduced in poorly controlled hypertensive patients, unfortunately, it is not possible to ascertain whether the participants in our study had poorly controlled hypertension and therefore this would need further investigation." (PMID 39186241, 2024). "Patients with a higher number (above 25th percentile) of CD34+/KDR+ and CD34+/VE-cadherin+ and lower of CD14+/endoglin+ cells (equal or below 75th percentile) were younger, with less years since diagnosis of hypertension, and with lower BP." (PMID 29304136, 2018). "Participants with hypertension had 4-fold increase in CD34 + KDR + EPC subtype numbers compared to those without." (PMID 39186241, 2024). "According to univariate linear regression analysis, hypertension, heart failure, decreased eGFR, circulating EPCs (both CD34+KDR+ and CD34+KDR+CD133+ cells), and increased inflammatory biomarkers (hsCRP, IL-1β, and TMAO) were all significantly associated with lower FMD." (PMID 30862856, 2019). "Indeed, R406 induced hypertension, inhibited VEGF-induced hypotension, and blocked KDR phosphorylation in vivo in preclinical models, providing indirect but compelling evidence that hypertensive effect of R406 in the clinic may be mediated through KDR." (PMID 26756335, 2016). "In contrast, CC-509 inhibits KDR cell activity to comparable levels at 10-fold higher concentrations than R406 and at levels reached only briefly at minimum efficacious exposures in rodents (data not shown), suggesting it would be unlikely to trigger KDR-dependent hypertension in human patients." (PMID 26756335, 2016).